IL6 (interleukin 6)
Diseases named in the same sentence as IL6 in open-access papers (continued):
Sharing a sentence is not in itself a finding about the gene and the disease.
tumor (continued). "M2b cells are induced by immune complexes, lipopolysaccharides, IL-1R and TLRs ligands; they produce cytokines such as IL-1, IL-6, TNF-α, and IL-10, acting in the metastasis control, suppressing tumor growth and inducing a Th1 response." (PMID 28970834, 2017). "Interestingly, elevation in serum TNFα and IL-6 were prevented in Rab27-deficient LLC tumor-bearing mice where serum Hsp70/90 and EV levels were not elevated, suggesting that elevated serum Hsp70 and Hsp90 mediate the systemic increase of inflammatory cytokines in tumor hosts." (PMID 28928431, 2017). "One of the most important effects exerted by OPN following CAF activation is the modulation of tumor-specific EMT through the secretion of TGF-β and IL-6." (PMID 28769537, 2017). "Genes such as IL6, GAB1, and VANGL1, were upregulated both in the tumor buds and in the microenvironment." (PMID 28687755, 2017). "The anti-tumor M1 TAMs produce IL-12, IL-6 and CXCL9 to stimulate the immune system, and express iNOS to kill tumor cells directly through production of nitric oxide." (PMID 29037250, 2017). "In the same model, S-adenosylmethionine (SAMe) and methylthioadenosine (MTA) inhibited IL-6/STAT3 and lowered tumor burden." (PMID 29108270, 2017). "Using multiplex ELISA, we observed a significant reduction in tumor cytokine levels of TNF (P = 0.002), and IL-6 (P = 0.014) in Losartan-treated compared to control tumors." (PMID 28416734, 2017). "Treatment of Balb/c mice injected with PC-9 or PC-9GR cells with 1 mg/mL metformin and 250 mg/L gefitinib for 30 days was found to block tumor growth of TKI-resistant xenografts, decrease IL-6 secretion and expression as well as reverse EMT." (PMID 28481268, 2017). "IL-6 (+) tumor stromal cells also showed positive correlations with α-SMA (+) CAFs, CD68 (+) and CD163 (+) tumor stromal TAMs." (PMID 28114366, 2017). "In our study, compared with the control cells, supernatant-treated RAW 264.7 macrophages released small quantities of NO, IL-6, and TNF-α and a large quantity of TGF-β, suggesting that the macrophages acquired tumor-promoting activities." (PMID 29155869, 2017). "Inflammatory cytokines, such as IL-6 and CXCL8, are known to support M2 macrophage polarization, whereas TGF-β recruits and retains macrophages at the tumor site and enables effective tumor evasion of the host immune system." (PMID 28052009, 2017). "Notably, we reported that expression of MFI2-AS1 was associated with expression of acute-phase proteins such as IL6 and SAA1, which might indicate that MFI2-AS1 is involved in the positive regulation of genes responsible for tumor-promoting inflammation, a poor prognosis factor in ccRCC35." (PMID 28819235, 2017). "Elevated levels of inflammatory cytokines (IL-6, TGF-β, VEGF, HGF) at the tumour site enhance cellular proliferation and migration and also increase the risk of relapse and metastasis." (PMID 28315228, 2017). "IL-6 expression induced by etoposide activates the JAK1-STAT3 pathway which mediates anti-senescence and promotes tumor growth." (PMID 28928376, 2017). "IL-1β and KC/GRO were found in both xenografts and non-tumour bearing NOD-scid, whereas IL-6 and TNF-α were exclusively detected in xenograft tissue." (PMID 28417956, 2017). "IL-6 has been also found to play a central role in cancer dissemination and invasion through VEGF synthesis stimulation and this, consequently, enhances tumor vascularization and angiogenesis." (PMID 28927416, 2017). "Tumor immune evasion is mediated, at least in part, by a network of soluble immunomodulatory factors, such as IL-6 and IL-10, as well as transforming growth factor β (TGF-β), which are secreted by tumor, stroma, and inflammatory cells." (PMID 28536351, 2017). "Compared to vehicle treatment, E7046 increased the myeloid cell-derived anti-tumor cytokine TNF-α, and reduced the levels of pro-tumor CXCL1, IL-10, and IL-6." (PMID 28920002, 2017).
tumor (continued). "In human tumor biopsies maintained in ex vivo culture, EnAd mediated release of pro-inflammatory mediators such as TNF-α, IL-6, and HMGB1." (PMID 28345021, 2017). "Immunohistochemistry staining demonstrated lower numbers of positive-stained IL-6, STAT3 and HIF1 cells in tumor tissues developed from siRNA-IL-6 knockdown cells, as compared with that of the CSC-derived xenografts." (PMID 28878571, 2017). "It is interesting that patient 14 experienced a significant increase in CRP, IL-6, and TNF-α level, but a significant decrease in tumor marker CEA levels." (PMID 29268708, 2017). "Co-stimulation with G-CSF and IL-6 induced a higher level of phospho-STAT3 in neutrophils, stimulating angiogenesis and tumor growth." (PMID 28099912, 2017). "3xTg-AD mice had an increased pro-inflammatory response characterised by the production of pro-inflammatory mediators such as tumour necrosis TNF-α, IL-6, CCL5 and CXCL-1, as well as an increase in immune cell infiltration to the sites of infection." (PMID 28284226, 2017). "Expression of tumor-induced factors responsible for MDSCs’ differentiation and proliferation, such as, TGFβ, MMP9, IL-6, VEGF, CXCR4, CCL2 was upregulated in MDSCs from CD8 depleted NLGP immunized mice, that was in downregulation after NLGP treatment." (PMID 28414726, 2017). "In gene expression arrays, the overexpression of TLR4 in tumor cells correlated with gene expression of ATF-3, IL-6, CDH13, CXCL-1 and TFPI." (PMID 28982115, 2017). "Tumour‐derived mediators, such as TGF‐β, IL‐1β and IL‐6, as well as cytokines produced by T cells, such as IFN‐γ, IL‐4 and IL‐10, promote MDSCs population expansion and support their immunosuppressive activity." (PMID 28276625, 2017). "FAPα-positive cells in tumor microenvironment can produce high levels of inhibitory factors such as TGF-β, IL-6, and IL-10." (PMID 28881756, 2017). "In order to determine the mechanism induced by MAP17 overexpression in tumor cells, we looked for NFAT2 and IL-6 expression, known attractant of inflammasome." (PMID 29228712, 2017). "IL-6 was disrupted by transcription activator-like effector nucleases (TALEN) in HCCLM3 cells, and was used to evaluate the role of IL-6 on tumor cell proliferation, apoptosis, invasion and key signaling pathways involved in sorafenib and/or IFNα therapy." (PMID 29100435, 2017). "We further measured the level of cytokines TNFα, IL-1β, IL-6, IL-17, IL23 and Cox-2 in tumor and normal tissues collected from the mouse colon using RT-qPCR." (PMID 28704539, 2017). "Two targets, IL-4Rα and cannabinoid receptor 2 (CB2), were validated and confirmed to regulate both IL-6 and IL-10 production in TAMs, contributing to autocrine/paracrine activation of STAT-3 in macrophages and tumour cells." (PMID 28381274, 2017). "There are studies have documented blockade of IL-6/GP130 signaling induces apoptosis and inhibits tumor cell growth in vitro or in vivo." (PMID 28672024, 2017). "In terms of tumor cell invasion, IFN-α or sorafenib increased the invasion ability of tumor cells although IL-6 has insignificant effect on tumor cells." (PMID 29100435, 2017). "Common up-regulated genes are related to transcription regulation (HMBOX1, LINC00340, NEXN-AS1), immune response (CD86, IL6, IFIT2) and the last two are potential tumor suppressors (LRRC2 and SPINK6)." (PMID 28035074, 2017). "We then confirmed pro-angiogenic cytokines (IL8 and IL6), TIMP-2, and MMPs (MMP-2 and MMP-9) in the isolated tumor tissues by IHC." (PMID 28659184, 2017). "STAT3 abnormal activity accelerates IL-6, HIF1α and VEGF, specifically in the tumor microenvironment." (PMID 27861147, 2017). "All three KD groups displayed significantly enhanced expression of IL-6 and/or CRP in the liver of the tumor bearing mice." (PMID 28915665, 2017). "The IL-17-induced IL-6 activates STAT3 and increases the expression of pro-angiogenic factors such as IL-8, MMP2, and VEGF to promote angiogenesis and tumor growth in vivo." (PMID 28978186, 2017).
tumor (continued). "Apart from the pro-angiogenic effects of this growth factor, paracrine interactions between tumor cells and BMSC were observed: stimulation of stromal cells with FGF-beta induces an increase of IL-6 secretion." (PMID 28099912, 2017). "Of these, Interleukin-6 (IL-6) and Stromal-Derived Factor-1 (SDF-1) are arguably the most significant in MM and AML pathogenesis and have been shown to be stimulated by tumour cell/BMM cell interactions." (PMID 28350342, 2017). "At concentration of the dual PI3Kδ/γ inhibitor duvelisib, which can be achieved in vivo we saw a decrease in AKT phosphorylation at s473 after tumour activation by bone marrow stromal cells (BMSC) and interleukin-6." (PMID 28282033, 2017). "IL-6 role in tumor development was initially described in pristane-induced peritoneal plasma cell tumors (PCT), where it was shown that IL-6 is the principal factor promoting the growth of PCT." (PMID 28978005, 2017). "The trimeric interaction of IL-6 with soluble IL-6R and the common gp130 subunit is known to activate STAT3 and promote tumor growth." (PMID 29207662, 2017). "IL-6 and TNF-α were also more expressed within the Klrk1+/+ tumour demonstrating that NKG2D has a significant influence on the tumour microenvironment, boosting the production of key pro-inflammatory cytokines." (PMID 28128200, 2017). "IL-6 secretion can activate VEGF expression and thus contribute to angiogenesis, cell proliferation and survival of tumor cells." (PMID 28903416, 2017). "Tumour-associated macrophages (TAM) have a TAM1 phenotype in the early stages of the tumour and promote tumour progression by secreting proinflammatory cytokines such as IL-6, TNF-Alfa,IL-23, and iNOS, involved in tumour initiation and tumour promotion." (PMID 28275390, 2017). "It has been described, that in RCC circulating cytokine levels, including IL-6, are increased in advanced RCC patients treated with sunitinib from baseline values before tumor progression." (PMID 28903416, 2017). "We further analyzed the percentages of IL-17A-, IL-6-, IFN-γ-, IL-4- and GM-CSF-producing Th cells (T helper cells) in tumor-infiltrating lymphocytes (TILs) from H7 tumor-bearing mice treated with Sc-4F or L-4F." (PMID 29245934, 2017). "We further found that treatment of tumor cells with siRNAs against P2X7R reduces, and treatment with a potent receptor agonist, BzATP, stimulates the production and release of IL-6, IL-8 and MCP-1." (PMID 28389503, 2017). "In previous studies, the express of certain cytokines increases following bacteria treatment, which contributes to the prevention of tumor growth and metastasis, such as TGF-a, IL-6, and IL-12." (PMID 29206859, 2017). "OS-derived extracellular vesicles (OS-EVs) contribute to establish a metastatic niche through induction of IL-6 production by mesenchymal stem cells (MSC), which in turn sustain tumour growth and progression." (PMID 29246026, 2017). "The breadth of responses includes anti-tumor effector (Granzyme B, IFN-γ, MIP-1α, TNF-α), stimulatory (GM-CSF, IL-2, IL-8), regulatory (IL-4, IL-13, IL-22), and inflammatory (IL-6, IL-17A) functions." (PMID 29157295, 2017). "Compared to their normal counterpart, tumor-derived Lineage-EpCAM-CD73+CD90+ cells showed enhanced expression of the immunosuppressive ligand PD-L1, a higher constitutive secretion of IL-6 and increased basal αSMA levels." (PMID 28878242, 2017). "One important mechanism of IL-6 procancerous action is activation of epithelial STAT3, a critical component of tumor-stimulating signaling in colon and other organs." (PMID 28350804, 2017). "Because IL-6 is a critical modulator of malignant features of cancer cells and the RB pathway is impaired in the majority of cancers, hsa-miR-140 might be a promising therapeutic tool that disrupts linkage between tumor suppressor inactivation and pro-inflammatory cytokine response." (PMID 28099924, 2017).
tumor (continued). "By analyzing tumor tissues, we showed that patients with high ST6GALNAC1 and IL-6 mRNA expression were BCG responders." (PMID 28903359, 2017). "In fact, the tumor microenvironment secretes many factors such as GM-CSF, VEGF, SCF, IL-6, IL-10, IL1β, PGE2, cyclooxygenase enzyme (COX) and the complement component C5a which promote recruitment and accumulation of immature MDSCs." (PMID 28609459, 2017). "Monocytes and macrophages recruited to the tumor directly regulate cancer stem cells (CSC) through inflammatory cytokines IL-1, IL-6, and IL-8, which drive CSC self-renewal in their niches." (PMID 28938604, 2017). "Inflammatory cytokines made by host and/or tumor cells, such as TNF-α, IL-1, IL-6 and IFN-γ, have been reported to induce cancer cachexia in animal models." (PMID 28915700, 2017). "At age of 21 months, even the tumor incidence was similar, the maximum tumor size increased significantly in DDB1F/F, Alb-Cre+/−, IL6−/− mouse." (PMID 27556180, 2016). "The transcription of the MMPs is induced by inflammatory cytokines, such as IL-1, IL-6, TNF-α, and growth factors such as EGF, HGF, and TGF-β, giving them a preponderant role in the chronic inflammation which is present in the tumour microenvironment." (PMID 26913068, 2016). "Malignant cells from many different cancer types constitutively produce inflammatory cytokines and chemokines that are important in tumor growth and cancer progression, TNF and IL-6 being the most commonly reported." (PMID 26871292, 2016). "Co-treatment also significantly reduced levels of pro-tumorigenic cytokines including TGF-β, VEGF, IL-6, IL-10, and MCP-1 in the ascites while increasing IFN-γ production by CD8+ effector T cells in the tumor ascites." (PMID 27852034, 2016). "To explore if our in vitro discovery of the promoter role of IL-6 in the self-renewal of CD133+ cells can be demonstrated in vivo, we performed investigations using human tumor xenografts in nude mice." (PMID 26675547, 2016). "High levels of various soluble mediators were found in the peripheral blood and/or tumor microenvironment of HNSCC, such as VEGF, PGE2, TGF-β, IL-6, and IL-10." (PMID 27044404, 2016). "We found that IL-6 neutralization led to a significant decrease in PDSC5 and MK16-Ras tumour cell growth relative to control IgG (1.8- and 1.9-fold, respectively)." (PMID 27272654, 2016). "Most tumor-promoting cytokines, such as TNF-α and IL-6 are produced by lamina propria macrophages and dendritic cells (DC) during early states of CRC development." (PMID 27679575, 2016). "Levels of IL-6, IL-1β, and tumour necrosis factor-α (TNF-α) in tumour tissue were 6.41−, 1.97−, and 1.83-fold higher in mice treated with HTiO2 NPs and US than in saline-treated control animals." (PMID 26996446, 2016). "Upregulation of inflammatory cytokines (e.g., IL-6 and TNF-α) in livers with chronic injury is known to support tumor-promoting microenvironments." (PMID 26821924, 2016). "The following section will highlight the induction of EMT in various tumor cells in response to CAF-derived TGF-β and IL-6." (PMID 27023622, 2016). "Nevertheless, inhibition of IL-6 signaling resulted in delayed PDAC progression from pancreatic intraepithelial neoplasia, and reduced primary tumor growth and recurrences in vivo." (PMID 27167341, 2016). "The levels of IL-6, IL-12p70 and TNF-α were substantially increased compared to PBS-treated tumor-bearing mice." (PMID 27008707, 2016). "DDP promoted tumor growth at the 10th day after the first DDP administration, but was then retarded by IL-6 neutralizing antibody treatment at the 14th day." (PMID 27285760, 2016). "While spleen cells of both control mice and vaccinated mice produced increased levels of IL-4 in the presence of the tumor-conditioned medium, the amount produced was less than that seen for IFN-γ or the inflammatory mediators IL-6 and TNF-α." (PMID 27598146, 2016).
tumor (continued). "During late infection stages, the secretion levels of IL-6, IL-1β, and IFN-β in the three clinical samples with neoplasms had significantly increased." (PMID 27252695, 2016). "Exosome cytokine proteomic profiles responses in 4THM and EMT6 tumor‐bearing mice were regulated by CD200:CD200R interactions, with attenuation of both IL‐6 and IL‐17 in 4THM CD200tg mice, and enhanced levels in 4THM CD200R1KO mice." (PMID 26725371, 2016). "Direct correlation between IL6, AKT and NF-kB reduced increased tumor growth and metastasis in mouse xenografts since IL-6 feedback loop, which is also validated as a protective mechanism in cells under stress condition." (PMID 27285760, 2016). "In contrast to IL6, TNFR1-mediated signaling pathway promotes HCC development, and deletion of TNFR1 reduced tumor incidence." (PMID 27556180, 2016). "In particular, the Hes1-mediated suppression of Pparg perpetuates the autocrine inflammatory activity of tumor pancreatic cells, inducing the production of inflammatory mediators, such as TNF- α, IL-6 and IL-1β." (PMID 27929540, 2016). "Constitutive expression of IL-6, TGF-β1, IL-17A, VEGF, IL-4, IL-10 and IDO by tumor cells as a major component of immune escape and immunosuppression in human EOC." (PMID 27118139, 2016). "Suppressing IL-6 significantly reduced growth and metastasis in both SOSP-9607 and F5M2 nude mouse primary tumour models, in accordance with the in vitro results." (PMID 26623559, 2016). "To gain further insight into the involvement of the IL6-p-STAT3-MIR155-3p pathway in autophagy in vivo, we tested the effects of IL6 and MIR155-3p knockdown on tumor growth." (PMID 27163161, 2016). "Altered secretion profile of leptin, and adiponectin, and other inflammatory adipokines such as IL-6 and TNF-α, by interacting with signaling network, accelerate neoplasia." (PMID 27980732, 2016). "BZLF1 also was found to enhance the tumor formation by BZLF1-deleted LCL in SCID mice, through increased expression of IL-6 and IL-10." (PMID 26967558, 2016). "Upon PDT, the targeted conjugate-treated mice also had higher levels of IL-6, IL-17, CTL, effector T cells and lower level of TGF-β, as well as a delay in tumor growth through adoptive transfer of immune cells." (PMID 27853305, 2016). "Pro-inflammatory cytokines including tumor necrosis factor-α, RNAKL and IL-6 were reported to induce VEGF-C induction in macrophages, astrocytes, fibroblasts, osteoclasts, as well as in tumor cells." (PMID 27383632, 2016). "The mRNA levels of colorectal inflammatory cytokines TNF-α, IL-1β, IL-6, CSF-1, and MCP-1, and COX-2 were increased in tumor and surrounding tissues from AOM/DSS-treated mice." (PMID 27557503, 2016). "Actors of this inflammatory process, such as tumor-associated macrophages (TAMs) or MDSCs and their secreted cytokines (IL-6, IL-1β, TNF) are now considered as key in promoting tumor progression." (PMID 27713124, 2016). "Among them, MCP-1 (CCL-2), IL-1b, IL-6, TNF-α were especially shown to be involved in the recruitment of immature cells into tumor microenvironment." (PMID 27993141, 2016). "Although IL6 promotes DEN-induced HCC development, its anti-tumor role in hepatocarcinogenesis was observed in current study." (PMID 27556180, 2016). "IL-1β increased stem-cell-like phenotypes, invasiveness, survival in a three-dimensional culture model, and estrogen-independent tumor growth of TG2-expressing MCF7 cells, which was attenuated by either anti-IL-6 or anti-IL-1β antibody treatment." (PMID 27609180, 2016). "Increased levels of inflammatory cytokines, such as IL-6, IL-8, and TNF-α, are known to promote migration, invasion and metastasis of various types of cancer including breast cancer." (PMID 26888313, 2016). "The cytokines that show elevated expression in human PMP and PDX ascites such as IL6, IP10, IL8, IL10, MCP‐1, and MIP‐1β have all been shown to perform autocrine and paracrine functions and regulate tumor–stromal cross talk." (PMID 26833741, 2016).